SETBP1 (SET binding protein 1)
Diseases named in the same sentence as SETBP1 in open-access papers (continued):
Sharing a sentence is not in itself a finding about the gene and the disease.
autosomal dominant mental retardation (1 paper, 2020). "Mutations in SETBP1 are known to cause autosomal dominant mental retardation and its haploinsufficiency is associated with mild neurodevelopmental delay and verbal development delay." (PMID 32096599, 2020).
bladder cancer (1 paper, 2021). "Among these five genes (GPC2, SETBP1, FGF11, APOL1, H1–2) related to the prognosis of patients with BC, there are no reports or experiments about these genes related to bladder cancer, except for H1–2." (PMID 34315402, 2021).
Blepharophimosis (1 paper, 2024). A fixed reduction in the vertical distance between the upper and lower eyelids with short palpebral fissures. "By reviewing the facial features, we found the occurrence of the main facial features commonly observed in SETBP1-HD presentation, represented by ptosis, blepharophimosis, a broad nasal bridge, and wide spaced eyes." (PMID 38520002, 2024).
disordered eating (1 paper, 2022). "We performed SMR to capture this in our analysis and found an association of disordered eating with CpG sites on SETBP1 and SEMG1." (PMID 35057575, 2022).
Epileptic encephalopathy (1 paper, 2020). A condition in which epileptiform abnormalities are believed to contribute to the progressive disturbance in cerebral function. "To summarize, we report the clinical details of three individuals carrying SETBP1 pathogenic mutations detected by NGS screening in two cohorts of individuals referred to our center for non-specific ID and for developmental and epileptic encephalopathy." (PMID 33391157, 2020).
External ophthalmoplegia (1 paper, 2024). Paralysis of the external ocular muscles. "In SETBP1 PATH3 NPCs compared to WT NPCs 655 gene sets were significantly dysregulated including: Hereditary Motor and Sensory Neuropathy Type 1; Familial Dystonia; widened subarachnoid space; minicore myopathy with external ophthalmoplegia (disorder); and Generalized Hyperkinesia." (PMID 39350244, 2024).
frontotemporal dementia (1 paper, 2024). Frontotemporal dementia (FTD) comprises a group of neurodegenerative disorders, characterized by progressive changes in behavior, executive dysfunction and language impairment, as a result of degeneration of the medial prefrontal and frontoinsular cortices. "DO terms unique to SETBP1 VUS2 NPCs included frontotemporal dementia; and substance related disorder." (PMID 39350244, 2024).
Headache (1 paper, 2021). Cephalgia, or pain sensed in various parts of the head, not confined to the area of distribution of any nerve. "Case 32, a 12-year-old boy with frequent headache episodes and hypospadias, had a missense variant in SETBP1, inherited from his father who was equally suffering from C1M and hypospadias." (PMID 33337535, 2021).
holoprosencephaly (1 paper, 2024). Holoprosencephaly (HPE) is a complex brain malformation resulting from incomplete cleavage of the prosencephalon, occurring between the 18th and 28th day of gestation, and affecting both the forebrain and face, which results in neurological manifestations and facial anomalies of variable severity. "Similar to the SETBP1 PATH2 and PATH3 NPCs the VUS2 NPCs significantly dysregulated gene sets relating to nervous system disorders including Neuropathy; Holoprosencephaly; Orbital separation diminished; and mechanical allodynia." (PMID 39350244, 2024). "The SETBP1 PATH2 NPCs had 23 gene sets significantly dysregulated compared to WT NPCs and included sciatic neuropathy; motor neuron disease; holoprosencephaly; and peripheral nervous system disorder." (PMID 39350244, 2024).
infantile epileptic encephalopathy (1 paper, 2024). an epileptic condition characterized by epileptiform abnormalities associated with progressive cerebral dysfunction. "In comparison to WT NPCs, SETBP1 PATH3 NPCs had a total of 367 DO gene sets dysregulated including mononeuritis of lower limb; early infantile epileptic encephalopathy; muscular disease; and status epilepticus." (PMID 39350244, 2024).
lipoma (1 paper, 2015). A benign, usually painless, well-circumscribed lipomatous tumor composed of adipose tissue. "In lipomas 3, 4 and 7 as well as the osteochondrolipoma, exon 3 of HMGA2 was fused to sequences from 18q12.3 which in lipomas 4 and 7 and the osteochondrolipoma consisted of the 3′-untranslated region of the SETBP1 gene." (PMID 26202160, 2015). "In lipoma 3, exon 3 of HMGA2 was fused with a sequence 10 kbp downstream of the SETBP1 gene." (PMID 26202160, 2015).
megaureter (1 paper, 2025). "No SETBP1 gene variants were detected in eight further cases of megaureter." (PMID 40123672, 2025).
neuroepithelial tumors (1 paper, 2019). "Germline pathogenic variants in SETBP1 cause Schinzel–Giedion syndrome, a severely debilitating condition that predisposes to neuroepithelial tumors." (PMID 31681433, 2019).
RASopathy (1 paper, 2024). Developmental syndromes caused by germline mutations (or in rare cases by somatic mosaicism) in genes that alter the Ras subfamily and mitogen-activated protein kinases that control signal transduction. "However, differently from RASopathies, SETBP1-HD typically presents with short instead of long palpebral fissures, and with normal stature." (PMID 38520002, 2024). "Therefore, both considering phenotypic features related to SETBP1-HD and SETBP1 function, this condition could be suggestive of as a RASopathy-like condition." (PMID 38520002, 2024).
sciatic neuropathy (1 paper, 2024). Disease or damage involving the SCIATIC NERVE, which divides into the PERONEAL NERVE and TIBIAL NERVE (see also PERONEAL NEUROPATHIES and TIBIAL NEUROPATHY). "In SETBP1 VUS2 NPCs, DO pathway terms in common with SETBP1 PATH2 and SETBP1 PATH3 NPCs included lesion of sciatic nerve; mononeuritis of lower limb; sciatic neuropathy; and peripheral nervous system disease." (PMID 39350244, 2024).
specific language impairment (1 paper, 2019). A language disorder characterized by difficulty in language acquisition despite otherwise normal development and in the absence of any obvious explanatory factors. "Among the candidates for domestication found to be upregulated it is worth highlighting SETBP1, which encodes a SET binding protein and which is a candidate for specific language impairment (SLI)." (PMID 30936846, 2019).
Stomach adenocarcinoma (1 paper, 2023). "The pan-cancer analysis of SETBP1 showed that SETBP1 overexpression should be given special attention in Bladder Urothelial Carcinoma (BLCA) and Stomach adenocarcinoma (STAD)." (PMID 37150818, 2023).
Stroke (1 paper, 2025). Sudden impairment of blood flow to a part of the brain due to occlusion or rupture of an artery to the brain. "In a study investigating stroke outcomes, SETBP1 mutations were identified in stroke patients, with CHIP carriers exhibiting distinct profiles of cardiovascular risk." (PMID 39997650, 2025). "SETBP1 has been associated with CHIP, a condition linked to an increased risk of cardiovascular diseases, including stroke." (PMID 39997650, 2025). "While the direct role of SETBP1 in stroke pathogenesis is still being studied, its involvement in clonal hematopoiesis suggests that it may contribute to an increased risk of ischemic stroke through mechanisms involving inflammation and vascular dysfunction." (PMID 39997650, 2025).
urothelial carcinoma (1 paper, 2021). A malignant neoplasm derived from the transitional epithelium of the urinary tract (urinary bladder, ureter, urethra, or renal pelvis). "However, the role of GPC2 and SETBP1 in urothelial carcinoma is not certain due to the lack of sufficient studies." (PMID 34315402, 2021).
tumor (30 papers, 2014 to 2025). "In this work, we determined that SETBP1 mutations were connected with genomic mutational burden, tumor immunogenicity, and importantly, ICI treatment sensitivity." (PMID 37535001, 2023). "Subsequently, a series of tumor immunogenicity and immunotherapeutic response-relevant molecular signatures were presented with a heatmap according to SETBP1 mutational status." (PMID 37535001, 2023). "It is now widely recognized as a tumor-associated gene, and alteration of SETBP1 expression has been implicated in several tissue-specific diseases, including cancer." (PMID 35898891, 2022). "The SET binding protein 1 (SETBP1) has been implicated in the pathogenesis of several cancers and plays a dual role as an oncogene and a tumor suppressor gene." (PMID 35898891, 2022). "The favorable tumor immunogenicity of SETBP1 mutations may explain the enhanced efficacy of ICI treatment." (PMID 37535001, 2023). "Mutated SETBP1 also enhanced the capacity of the MAPK signal to facilitate tumor progression." (PMID 37535001, 2023). "In summary, by using clinically expanded ICI cohorts, we uncovered that SETBP1 mutations were associated with favorable tumor immunogenicity and determined the sensitivity to cancer immunotherapies, which provides a potential biomarker for evaluating cancer ICI treatment response." (PMID 37535001, 2023). "The gene cluster (LRP1, ACVR2A, and SETBP1) could be a good biomarker of these patients with a family risk, which was characterized by right-sidedness, high tumor mutational burden, and high microsatellite instability." (PMID 35814400, 2022). "Next, we describe the prevalence of SETBP1 mutations in congenital diseases and in hematologic malignancies, exploring how its alterations might contribute to tumor development and provoke clinical effects." (PMID 28881700, 2017). "ASXL1 mutations are frequent, with the disease displaying a higher prevalence of ETNK1, SETBP1, and EZH2 mutations in comparison to other MDS/MPN overlap neoplasms." (PMID 37370785, 2023). "Additional immunological analyses revealed that favorable immune infiltration, tumor immunogenicity, and immune response circuits were enriched in SETBP1-MUT patients." (PMID 37535001, 2023). "SETBP1 acts as a transcription factor in biological mechanisms and involves in tumor progression and immune regulation." (PMID 37535001, 2023). "Recent evidence has shown that SETBP1 mediates immune regulation and anti-tumor immune infiltration." (PMID 37535001, 2023). "The expressions of SETBP1 gene in different tumor stages of BLCA, ESCA, KICH, KIRC, OV and STAD were also significantly different (P < 0.05)." (PMID 37150818, 2023). "We used next-generation RNA sequencing (RNA-seq) data from The Cancer Genome Atlas (TCGA) to explore the correlation between SETBP1 expression and tumor progression." (PMID 35898891, 2022). "We showed that SETBP1 expression was significantly lower in GC tissues than in adjacent non-tumor tissues in the TCGA database." (PMID 35898891, 2022). "In the high SETBP1 expression group, the neuroactive ligand receptor interaction signaling pathway is related to tumor TNM stage, lymph node metastasis, and poor prognosis with GC." (PMID 35898891, 2022). "We found SETBP1 expression levels in GC tissues to be significantly lower than in adjacent non-tumor tissues in the TCGA database." (PMID 35898891, 2022). "We found SETBP1 expression to be significantly lower in GC tissues than in adjacent non-tumor tissues (P<0.0001)." (PMID 35898891, 2022). "We assessed the relationship between SETBP1 expression and clinicopathological features, finding that high SETBP1 expression was significantly correlated with tumor differentiation (P=0.001)." (PMID 35898891, 2022).
tumor (continued). "While SETBP1 can reduce the progression of NSCLC as a tumor suppressor and can be used for a prognostic biomarker in NSCLC." (PMID 33680913, 2020). "JMML is a pathology depicted by a very low gene mutation frequency as compared to other neoplasms such as CMML; somatic or germline RAS pathway involvement occurs in 89% of cases, and frequently, secondary alterations involve SETBP1 and JAK3 genes." (PMID 28881700, 2017). "While ASXL1 and SRSF2 mutations may reflect age-related clonal hematopoiesis, SETBP1 is more strongly associated with secondary AML, CMML, and aCML—often co-occurring with ASXL1 and SRSF2 in those neoplasms." (PMID 41278291, 2025). "As for OV, Qiao and colleague reported that SETBP1 could maintain the Cancer Stem Cell (CSC)-like phenotype of tumor cells via the SET/PP2A axis." (PMID 37730669, 2023). "Further studies with larger sample sizes and on the possible dynamic regulatory mechanism by which SETBP1 contributes to GC are required to determine whether SETBP1 functions as an oncoprotein or tumor suppressor in GC." (PMID 35898891, 2022). "Moreover, the chi-square test and logistic regression analyses showed that SETBP1 expression correlates significantly with tumor differentiation." (PMID 35898891, 2022). "At the same time, we found two other tumor suppression genes, SETBP1 and SULF1." (PMID 35433683, 2022). "In addition, SETBP1 expression differed significantly between groups classified by tumor differentiation." (PMID 35898891, 2022). "Therefore, SETBP1 can function either as an oncoprotein or tumor suppressor, and further studies on its role in GC are required." (PMID 35898891, 2022). "Our results here suggest that Celastrol could also be effective for treating SETBP1 activation-induced neoplasms." (PMID 27863435, 2016). "Significant African-ancestry-specific findings include an elevated tumour mutational burden, increased percentage of genome alteration, a greater number of predicted damaging mutations and a higher total of mutational signatures, and the driver genes NCOA2, STK19, DDX11L1, PCAT1 and SETBP1." (PMID 36045292, 2022). "For the tumor tissue, we also detected correlated expression of STAiR1 and the adjacent oncogenic SETBP1, which might just be a coincidental consequence of the chromatin state of the entire locus, or point at some cis interaction between both transcripts or loci." (PMID 24594072, 2014). "It is noteworthy that PDRWH also identified known tumor-specific drivers that were missed by other methods, such as ABL2 for BRCA, SETBP1 for KIRC, NIN and TOP2A for STAD." (PMID 38683860, 2024). "We found that the expressions of SETBP1 in BLCA, ESCA, KICH, KIRC, OV and STAD were significantly different from those in normal tissues and in different tumor stages." (PMID 37150818, 2023). "The SETBP1 expressions of tumor tissues were compared to the normal tissues of the same origin, except of MESO, THYM and UVM in which the SETBP1 expression data was missing." (PMID 37150818, 2023). "Therefore, SETBP1 may promote tumor progression by regulating various signaling pathways." (PMID 35898891, 2022). "SETBP1 binds an oncoprotein SET and the resulting heterodimer inhibits a phosphatase PP2A that acts as a tumour suppressor in many cancer cells." (PMID 30367089, 2018). "These include genes involved in hematological system development such as SETBP1 and NRP1 and putative tumor suppressor genes such as PARD3 and LRIG1." (PMID 28806978, 2017). "Intriguingly, SETBP1 interacts with RAS/MAPK cascade by inhibiting the activity of the tumor suppressor PROTEIN PHOSPHATASE 2A (PP2A), which regulates this pathway through the stabilization of SET, another important tumor suppressor." (PMID 38520002, 2024).
cancer (29 papers, 2014 to 2025). A tumor composed of atypical neoplastic, often pleomorphic cells that invade other tissues. "Variants in p.Asp868 lead to a large increase in SETBP1 protein levels, with an increased risk of cancer in comparison to other SGS variants." (PMID 40859069, 2025). "In contrast, somatic variants in SETBP1 are associated with hematological malignancies and exhibit varying evidence for predisposing or promoting cancer in other adult tissue systems." (PMID 38165902, 2024). "Somatic variants in SETBP1 are associated with hematological malignancies and cancer development in other tissues in adults." (PMID 38165902, 2024). "Previous studies support that surpassing a higher functional threshold (i.e., more damaging or impacting variants) is required for SETBP1-driven cancer." (PMID 38165902, 2024). "As a new oncogene and potential marker of myeloid malignancies, somatic SETBP1 variants in other cancers were rarely studied." (PMID 37150818, 2023). "SETBP1 mutations in cancer were first reported as NUP98‐SETBP1 fusion genes in patients with T‐cell acute lymphoblastic leukemia." (PMID 37489294, 2023). "Accumulating evidence has shown that ASXL1 mutations inhibit cancer cell differentiation and that SETBP1 mutations promote cell proliferation, thus leading to AML progression." (PMID 37489294, 2023). "Previously several studies have revealed that SETBP1 mutations were associated with poor survival outcomes in cancers." (PMID 37535001, 2023). "On the contrary, we observed positive correlations between the expression level of SETBP1 and the level of cancer-associated fibroblasts in most tumors." (PMID 37150818, 2023). "This work identified a cluster of co-mutation genes (LRP1, ACVR2A, and SETBP1) and found these genes were significantly associated with a family history of cancer." (PMID 35814400, 2022). "SETBP1 belongs to a group of genes where identical point mutations can lead to cancer, when mutated somatically, or to severe developmental syndromes when occurring in the germline." (PMID 34193871, 2021). "We also report prioritized missense variants SETBP1:c.4129G > C and C7orf34:c.248C > T. These variants comprise promising candidates whose role in cancer pathogenicity needs to be explored further." (PMID 31681433, 2019). "Strikingly, most cancer cases in SGS are observed in patients with strongly activating germline SETBP1 mutations." (PMID 28346496, 2017). "Using droplet digital polymerase chain reaction (ddPCR) analysis, SETBP1 mutations were detected in all four compartments corroborating the concept that SETBP1 mutations occur in early cancer-initiating cells." (PMID 28881700, 2017). "Subsequent analysis of the SETBP1 mutation status of a further 70 aCMLs, 574 diverse hematological malignancies and 344 cancer cell lines revealed mutations in 24% cases." (PMID 28881700, 2017). "Individuals with germline mutations affecting D868 have enhanced cell proliferation in vitro and higher incidence of cancer compared to patients with other germline SETBP1 mutations." (PMID 28346496, 2017). "Association analyses between SETBP1 expression levels with clinical survival analysis, genomic heterozygosity and immune infiltration in different cancers revealed its complex role in the pathogenesis of cancers." (PMID 37150818, 2023). "Our findings suggest that SETBP1 mutations could be a promising biomarker in clinical cancer immunotherapies." (PMID 37535001, 2023). "Patients with mutations in LRP1, ACVR2A, and SETBP1 tend to have a family history of cancer." (PMID 35814400, 2022). "On the other hand, substitutions in residue D868 result in the greatest increases in protein levels, and are associated with a higher cell proliferation rate in vitro and a greater incidence of cancer as compared with patients with other germline SETBP1 mutations." (PMID 29861492, 2018).